WDR20 (WD repeat domain 20)
Description:
Regulator of deubiquitinating complexes. Activates deubiquitinating activity of complexes containing USP12. Anchors at the base of the ubiquitin-contacting loop of USP12 and remotely modulates the catalytic center of the enzyme. Regulates shuttling of the USP12 deubiquitinase complex between the plasma membrane, cytoplasm and nucleus.
Synonyms: DMR; MGC33177; FLJ33659; Bun107
Tractability: PROTAC: ubiquitination databases record sites on it; its protein half-life has been measured.
Gene: Protein-coding gene on chromosome 14 (102,139,503 to 102,224,847, forward strand). Ensembl gene ENSG00000140153.
Subcellular location: Cytoplasm; Nucleus
Pathways (Reactome):
Metabolism of proteins: Ub-specific processing proteases
Gene Ontology:
Molecular function: deubiquitinase activator activity; protein binding
Biological process: positive regulation of canonical Wnt signaling pathway; negative regulation of ubiquitin-dependent protein catabolic process
Cellular component: cytoplasm; nucleus; peptidase complex; nucleoplasm; plasma membrane
Genetic constraint (gnomAD): Loss-of-function variants: 3 observed, 39.25 expected, observed/expected ratio (o/e) 0.0764, 90% interval 0.034 to 0.2. The upper end of that interval is the gene's LOEUF score, 0.2, which puts it in group 1 of 6, group 1 being the genes least tolerant of losing a copy. Missense variants: 559 observed, 770.13 expected, observed/expected ratio (o/e) 0.73, 90% interval 0.68 to 0.78. Synonymous variants: 298 observed, 301.92 expected, observed/expected ratio (o/e) 0.99, 90% interval 0.9 to 1.09.
Homologues: Orthologues: chimpanzee WDR20 (99% identical), macaque WDR20 (99% identical), rabbit WDR20 (99% identical), mouse Wdr20 (98% identical), rat Wdr20 (98% identical), dog WDR20 (97% identical), pig WDR20 (95% identical), tropical clawed frog wdr20 (95% identical), mouse Wdr20rt (92% identical), zebrafish wdr20a (89% identical), guinea pig WDR20 (86% identical), zebrafish wdr20b (78% identical), and 2 more. Paralogues in human: DMWD (60% identical).
Diseases named in the same sentence as WDR20 in open-access papers:
WDR20 is named in the same sentence as 14 diseases in open-access papers, as found by Europe PMC text mining. Sharing a sentence is not in itself a finding about the gene and the disease. The quoted sentences say what the papers report.
prostate carcinoma (2 papers, 2015 to 2022). A carcinoma that arises from epithelial cells of the prostate gland. "Studies have shown that WDR20 has a positive or negative correlation with the occurrence of lymphoma, prostate cancer and other diseases." (PMID 35936896, 2022).
renal carcinoma (2 papers, 2018 to 2020). A carcinoma arising from the epithelium of the renal parenchyma or the renal pelvis. "Subsequent functional assays showed that exogenous WDR20 significantly inhibited the growth of renal carcinoma cells and induced apoptosis, which may be resulted from the deactivation of downstream ERK and protein kinase B/AKT signaling pathways." (PMID 33282547, 2020).
autism spectrum disorder (1 paper, 2023). A spectrum of developmental disorders that includes autism, and Asperger syndrome. "With regards to genes with probes at suggestive significance at school-age (WDR20, MOV10, and TAOK2), these have previously been linked to neurodevelopmental and psychiatric risk, such as autism spectrum disorder (ASD) and schizophrenia." (PMID 36385171, 2023).
breast carcinoma (1 paper, 2024). "To validate the results of our screens, we used Crispr/Cas9 technology to knockout (KO) the USP12, USP46, WDR20, and WDR48 genes either individually or in combination in at least two different mouse fibroblast and human breast cancer MDA-MB-231 cell clones, respectively." (PMID 39506038, 2024).
childhood asthma (1 paper, 2023). "The amino acid sequence of DMWD is similar to that of WD repeat domain 20 (WDR20), which is associated with childhood asthma." (PMID 37875944, 2023).
medulloblastoma (1 paper, 2021). A malignant, invasive embryonal neoplasm arising from the cerebellum. "Other novel genes identified in this study are associated with cancer, such as WDR20 with medulloblastoma and SUFU with renal cell carcinoma." (PMID 33809095, 2021).
cancer (2 papers, 2021 to 2022). A tumor composed of atypical neoplastic, often pleomorphic cells that invade other tissues. "TRAF7 has been partially studied in aquatic animals, and BAG3, WDR20 and FUT4 are mostly focused on wound tissue recovery and cancer treatment in medicine." (PMID 35936896, 2022).
WDR20 also shares sentences with these, for which no sentence is quoted: clear cell renal cell carcinoma (1 paper); glioblastoma (1); lymphoma (1); renal cell carcinoma (1); schizophrenia (1); stomach cancer (1); uterine cancer (1).